KLRC2 (killer cell lectin like receptor C2)
Description:
Immune activating receptor involved in self-nonself discrimination. In complex with KLRD1 on cytotoxic lymphocyte subsets, recognizes non-classical major histocompatibility (MHC) class Ib HLA-E loaded with signal sequence-derived peptides from non-classical MHC class Ib HLA-G molecules, likely playing a role in the generation and effector functions of adaptive natural killer (NK) cells and in maternal-fetal tolerance during pregnancy. Regulates the effector functions of terminally differentiated cytotoxic lymphocyte subsets, and in particular may play a role in adaptive NK cell response to viral infection. Upon HLA-E-peptide binding, transmits intracellular signals via the adapter protein TYROBP/DAP12, triggering the phosphorylation of proximal signaling molecules and cell activation.
Synonyms: CD159c; NKG2C; NKG2-C
Tractability: Antibody: UniProt places it where antibodies can reach, with high confidence; its Gene Ontology location is reachable by antibodies, with high confidence; UniProt predicts a signal peptide or a membrane-spanning region; the Human Protein Atlas places it where antibodies can reach.
Gene: Protein-coding gene on chromosome 12 (10,426,854 to 10,442,300, reverse strand). Ensembl gene ENSG00000205809.
Subcellular location: Cell membrane
Subcellular location (Human Protein Atlas): Plasma membrane
Pathways (Reactome):
Immune System: DAP12 interactions; DAP12 signaling
Gene Ontology:
Molecular function: activating MHC class Ib receptor activity; MHC class I protein complex binding; protein antigen binding; protein binding; transmembrane signaling receptor activity; MHC class Ib receptor activity
Biological process: natural killer cell mediated immunity; positive regulation of natural killer cell degranulation; positive regulation of natural killer cell mediated cytotoxicity; stimulatory C-type lectin receptor signaling pathway; cellular defense response; regulation of natural killer cell activation; signal transduction; immune response-regulating cell surface receptor signaling pathway; immune system process; regulation of natural killer cell mediated cytotoxicity
Cellular component: plasma membrane; receptor complex; cell surface
Genetic constraint (gnomAD): Loss-of-function variants: 8 observed, 17.02 expected, observed/expected ratio (o/e) 0.47, 90% interval 0.28 to 0.85. The upper end of that interval is the gene's LOEUF score, 0.85, which puts it in group 3 of 6, group 1 being the genes least tolerant of losing a copy. Missense variants: 127 observed, 187.35 expected, observed/expected ratio (o/e) 0.68, 90% interval 0.59 to 0.79. Synonymous variants: 41 observed, 57.01 expected, observed/expected ratio (o/e) 0.72, 90% interval 0.56 to 0.93.
Homologues: Orthologues: mouse Klre1 (22% identical), mouse Klri1 (22% identical), rat Klri1 (22% identical), rat Klre1 (21% identical), Drosophila melanogaster rgn (20% identical), rat Klri2 (20% identical), mouse Klri2 (19% identical), rat Klrh1 (19% identical), zebrafish si:ch211-170d8.8 (19% identical), zebrafish si:dkey-26c10.5 (19% identical), Caenorhabditis elegans clec-146 (17% identical), zebrafish si:ch211-193e13.5 (16% identical), and 4 more. Paralogues in human: KLRC3 (89% identical), KLRC1 (77% identical), KLRC4 (55% identical), CLEC12B (23% identical), KLRD1 (22% identical), CLEC7A (21% identical), CLEC12A (20% identical), KLRB1 (20% identical), KLRG1 (20% identical), CLEC9A (19% identical), KLRK1 (19% identical), OLR1 (19% identical), and 11 more.
Diseases named in the same sentence as KLRC2 in open-access papers:
KLRC2 is named in the same sentence as 84 diseases in open-access papers, as found by Europe PMC text mining. Sharing a sentence is not in itself a finding about the gene and the disease. The quoted sentences say what the papers report.
HCMV infection (119 papers, 2011 to 2025). "The adaptive-like NK cells featured high expression of CD3E, LAG3, and IL-32 with no expression of FCER1G and TCRs, consistent with published scRNA-seq data (except for low expression of KLRC2/NKG2C, the canonical markers for adaptive NK cells after human cytomegalovirus (HCMV) infection) 21,22." (PMID 40394087, 2025). "Besides, haematological malignant cells co‐cultured with NK cells under cytomegalovirus infection increased NKG2C+ (KLRC2) NK cell expansion and enhanced their anti‐tumour cytotoxicity." (PMID 35184420, 2022). "Furthermore, children (but not adults) bearing the KLRC2 deletion had significantly higher levels of anti-HCMV IgG antibodies, suggesting that NKG2C plays a role in the control of HCMV infection early in childhood." (PMID 27312142, 2016). "Notably, humans lacking one KLRC2 allele that encodes NKG2C receptor had a compromised NK cell differentiation during HCMV infection, with altered adaptive response and high anti-HCMV IgG titers." (PMID 28078307, 2016). "This NK2 subpopulation featured high expression of NKG2C KLRC2) and low expression of PLZF (PLZF), FcεRγ (FCER1G), EAT-2 (SH2D1B), and SYK (SYK), which are used as markers for memory NK cells in the context of human cytomegalovirus (HCMV) infection." (PMID 35501841, 2022).
COVID-19 (40 papers, 2020 to 2025). A disease caused by infection with severe acute respiratory syndrome coronavirus 2. "Another NK cell activating receptor (the NKG2C protein) encoded by the KLRC2 gene was previously implicated as a COVID-19 marker." (PMID 39470726, 2024). "The deletions of KLRC2 and, at a lower degree, the HLA-E* 0101 allele are independent risk factors for severe COVID-19, suggesting that genetic variants in the NKG2C/HLA-E axis have a significant impact on COVID-19 severity." (PMID 35625739, 2022). "The results indicated that KLRC2 deletion is a significant individual risk factor for severe COVID-19." (PMID 35062298, 2022). "Similarly, these same long-read assemblies enabled the discovery of three distinct structural haplotypes at the KLRC2 locus, a gene involved in immune cell maturation and the deletion of which has been associated with severe COVID-19 symptoms." (PMID 39042999, 2024). "The deletion of KLRC2 and HLA-E*0101/0103 allelic variants were evaluated in a study cohort of 361 patients, of which 92 had mild COVID symptoms, and 269 patients had severe COVID-19." (PMID 35062298, 2022). "The KLRC2 protein (also: NKG2C) can bind to CD94 and HLA-E to form a functional complex, and thus, the depletion of KLRC2 is likely to have a significant impact on the development of severe COVID-19." (PMID 37403156, 2023). "Moreover, deletion of the KLRC2 gene, which encodes the activating receptor NKG2C, has been linked to increased susceptibility to severe forms of COVID-19." (PMID 40650195, 2025). "On the one hand, the absence of the KLRC2 gene encoding NKG2C has been shown to increase the risk of severe COVID-19." (PMID 36768315, 2023). "Results obtained within this study indicate that the presence of deletion within the NKG2C/KLRC2 gene, as well as NKG2A rs7301582, HLA-E rs1264457, MICB rs065075, and MICA rs1051792 SNPs, could be associated with COVID-19 susceptibility and the severity of the disease." (PMID 41153412, 2025). "We studied the impact of Mw on the incidence of COVID-19 (corona virus disease 2019 caused by SARS-CoV-2) in a cohort–control study in front-line healthcare workers and its impact on the kinetics and repertoire of NKG2C+ANK cells in the context of the KLRC2 genotype." (PMID 35603154, 2022). "Comparison between the disease conditions indicated significantly stronger expression of certain NK cell receptors (CD160, KLRC2, KLRC3, KLRF1, KIR3DL2, NCR1, NCR3) along the SLEC lineage in mild COVID-19 compared to severe COVID-19." (PMID 36591270, 2022). "KLRC2 deletion was detected in 2 out of 6 with COVID-19, compared to 16 out of 44 without COVID-19 (p=0.6)." (PMID 35603154, 2022). "Differential expression of NK cell receptor genes, such as KLRC2 and KIR3DL2 in CD16+ CD8+ TEMRA-2 cells in mild COVID-19 compared with severe COVID-19 further strengthened the hypothesis of profound differences in NK-like differentiation between disease conditions." (PMID 36591270, 2022).
psoriasis (8 papers, 2014 to 2023). An autoimmune condition characterized by red, well-delineated plaques with silvery scales that are usually on the extensor surfaces and scalp. "For example, deletion of the KLRC2 gene, which encodes NKG2C, is associated with psoriasis and may have a role in the control of HCMV in children but not in bacterial infection caused by Chlamydia trachomatis." (PMID 29520269, 2018). "An association between KLRC2 deletion and psoriasis has also been reported." (PMID 27312142, 2016). "In the context of infection, KLRC2 deletion was shown to be associated with impaired outcomes to CMV, HIV infection and psoriasis." (PMID 27312142, 2016).
lymphoma (4 papers, 2020 to 2024). A malignant (clonal) proliferation of B- lymphocytes or T- lymphocytes which involves the lymph nodes, bone marrow and/or extranodal sites. "We therefore tested all EBV+ lymphoma patients and the respective controls for their HCMV-serostatus and KLRC2 variants." (PMID 37426645, 2023). "In contrast, low level or even lacking NKG2C+ NK cell responses, reflected by the combination of a negative HCMV-status and KLRC2 deletion variants, were highly associated with the development of EBV+ lymphomas." (PMID 37426645, 2023).
glioma (3 papers, 2020 to 2022). A benign or malignant brain and spinal cord tumor that arises from glial cells (astrocytes, oligodendrocytes, ependymal cells). "Although data on NKG2C in tumour are limited, KLRC2 was identified as one of the protective genes in lower‐grade gliomas, which was in line with its high expression in the cytotoxic CD8+ T cells in this study." (PMID 35184420, 2022). "The mRNA expression of CANX, HSPA1B, PSMC6, and TAP1 was high in gliomas, whereas that of KLRC2 was low." (PMID 32351547, 2020).
malaria (3 papers, 2020 to 2025). Malaria is a serious and sometimes fatal disease caused by a parasite that commonly infects a certain type of mosquito which feeds on humans. "Klrc2 is the only gene that exhibits a very low constitutive expression and responds neither to malaria nor to vaccination." (PMID 33202767, 2020).
gastric cancer (2 papers, 2019 to 2025). A primary or metastatic malignant neoplasm involving the stomach. "For example, gastric cancer cells and many immune cell subtypes can interact with cytotoxic/exhausted CD8+ T cells and/or NK cells via HLA-E-KLRC1/KLRC2, suggesting that the anti-KLRC1 antibody may be a potential therapeutic option in gastric cancer." (PMID 41316282, 2025).
colon cancers (1 paper, 2022). "ILC1s expressed inhibitory receptors and underwent inhibitory functional conversion in late stage colon cancers while ILC1s in early-stage tumors expressed high levels of activating receptors (KLRD1, NCR1, KLRC2, KLRB1C) while late-stage colon cancers expressed inhibitory markers (KLRE1, KLRA7)." (PMID 36189323, 2022).
kidney transplant (1 paper, 2025). A surgical procedure in which one or both kidneys from a donor are implanted into a recipient. "In conclusion, our study highlights the substantial impact of genetic factors related to NK-cell functionality, specifically missing self, polymorphisms in KLRC2 rs9916629‐C/T, and, in DSA-positive patients, FCGR3A, on the risk of MVI occurrence in kidney transplant recipients." (PMID 39402708, 2025).
osteosarcoma (1 paper, 2018). A usually aggressive malignant bone-forming mesenchymal neoplasm, predominantly affecting adolescents and young adults. "Among these DEGs, there were some genes that have not been reported in osteosarcoma, such as KLRC2, SCG2, so these might reveal the novel mechanism of sorafenib inhibition of osteosarcoma." (PMID 29744300, 2018).
trachoma (1 paper, 2016). "The association between KLRC2 genotypes and clinical signs of trachoma was investigated by multivariate logistic regression including age and gender in the model." (PMID 27312142, 2016). "In this study, we compare and quantify the frequency of KLRC2/NKG2C deletion in different African populations (East- and West-Africa) where trachoma is or has been endemic at the time of sample collection." (PMID 27312142, 2016).
vitiligo (1 paper, 2025). Generalized well circumscribed patches of leukoderma that are generally distributed over symmetric body locations and is due to autoimmune destruction of melanocytes. "Moreover, the decreased KLRC2 expression in this T cell subset in patients suggests its potential as a diagnostic marker for vitiligo, highlighting its relevance in disease pathogenesis and biomarker development." (PMID 41438750, 2025). "Here, we demonstrate for the first time that KLRC2+ NK cells are markedly reduced in vitiligo patients and exhibit features enriched for apoptosis-related and immunoregulatory pathways." (PMID 41438750, 2025). "Upregulation of KLRC2 in vitiligo skin lesions has been reported, suggesting its potential involvement in local immune responses." (PMID 41438750, 2025). "To further validate the reduction of KLRC2+ NK cell subsets, we collected samples from 7 vitiligo patients of different age groups and 30 healthy controls." (PMID 41438750, 2025). "Our analysis revealed dynamic alterations and functional roles of KLRC2+ NK cells, Treg cells, FCGR3A+ Cytotoxic CD8 + T cells, and EGR1+ B cells, opening new avenues for systemic immunology-oriented research in vitiligo." (PMID 41438750, 2025). "Similarly, we found that the NK cell subset KLRC2+ is reduced in non-segmental vitiligo patients, suggesting that different NK cell subsets may play distinct roles in disease development." (PMID 41438750, 2025).
infection (70 papers, 2010 to 2025). The state of being infected such as from the introduction of a foreign agent such as serum, vaccine, antigenic substance or organism. "Comparisons across the early- and late-stages of infection showed that cells from CHs had an early expression of genes associated with exhaustion (PDCD1, ENTPD1), and cytotoxicity, including NK-like genes NKG7, GNLY, KLRC2, and KLRC3 (encoding for NKG2C and NKG2E, respectively)." (PMID 36477661, 2022).
tumor (54 papers, 2012 to 2025). "Moreover, like TCGA, high LGG tumor expression of KLRC2 is also associated with the SPANK and memory CD8+ T cell phenotypes and improved prognosis of CGGA LGG patients." (PMID 34539622, 2021). "Aberrant expression of KLRC2 in NK cells is critical for maintaining the microenvironment essential for tumor initiation and progression." (PMID 41438750, 2025). "In contrast to TCGA LGG dataset, high tumor expression of KLRC1 and KLRC2 in CGGA LGG patients were associated with improved prognosis, but not KLRC3, KLRC4 or KLRK1." (PMID 34539622, 2021). "Tumor-infiltrating clusters NK1 and NK5 showed high expression of NK-activating receptors, including NKG2D-DAP10 (KLRK1/HCST), NKG2C (KLRC2), CD94 (KLRD1), and NKp30 (NCR3), suggesting that they were robustly activated." (PMID 40315330, 2025). "Comparing T cell gene expression between treatments revealed a significant increase in Klrk1, Klrc2, Klrd1, Fasl, and Sema4a in CD4 T cells at the tumor site after HVJ-E/OX40 antibody injection." (PMID 39534532, 2024). "One major class of genes controlling both activating and inhibitory NK cell receptor groups (NKGs) is Klrc1 [NKG2A], Klrc2 [NKG2C], and Klrk1 [NKG2D] and are involved in specific interactions with the MHC of tumor cells and virally infected cells." (PMID 31009335, 2019). "High tumor expression of KLRC1 and KLRC2 were also associated with improved survival in the CGGA LGG patient cohort, but not KLRK1, KLRC2 or KLRC4." (PMID 34539622, 2021).
cancer (12 papers, 2016 to 2025). A tumor composed of atypical neoplastic, often pleomorphic cells that invade other tissues. "KLRC2 deletion is associated with reduced numbers of mature NK cells and increased susceptibility to HIV infection, certain autoimmune conditions, and cancer." (PMID 31697647, 2019). "A strong cell–cell interaction (CCI) between cancer subclusters (G0, G1 and G3) and cytotoxic/exhausted CD8+ T cells and/or NK cells was predicted based on the HLA‐E‐KLRC1/KLRC2 pair." (PMID 35184420, 2022).
bacterial infections (3 papers, 2016 to 2025). "Interestingly, the association between KLRC2/NKG2C deletion and intracellular bacterial infections has not been described so far." (PMID 27312142, 2016).
infectious disease (2 papers, 2016 to 2023). A disorder directly resulting from the presence and activity of a microbial, viral, or parasitic agent in humans. "Contrary to KLRC2 deletion, HLA-C2 and KIR2DL2/2DL3 heterozygosity was shown to be associated with conjunctival scarring and a number of different KIR and HLA constellations have been shown to be associated with various infectious diseases, reproduction and survival." (PMID 27312142, 2016).
KLRC2 also shares sentences with these, for which no sentence is quoted: viral infections (54 papers); co-infection (24); HIV-1 infection (12); acute myeloid leukemia (11); leukemia (9); influenza (8); glioblastoma (5); hantavirus infection (4); multiple myeloma (4); multiple sclerosis (4); chronic hepatitis (3); ovarian carcinoma (3); tuberculosis (3); viral hepatitis (3); acute graft versus host disease (2); autoimmune disease (2); B-cell lymphoma (2); chronic GvHD (2); hematologic malignancies (2); hepatocellular carcinoma (2); immune dysfunction (2); lung disease (2); melanoma (2); myelogenous leukemia (2); acute lymphoblastic leukemia (1); adenocarcinoma (1); AIDS (1); allergies (1); ankylosing spondylitis (1); Arthritis (1).
A further 37 diseases each share a sentence with KLRC2 in 1 paper.